H2AX (H2A.X variant histone)
Diseases named in the same sentence as H2AX in open-access papers (continued):
Sharing a sentence is not in itself a finding about the gene and the disease.
cancer (continued). "In some cases there is substantial induction of γ-H2AX foci with exposure to high levels of ionizing radiation and cancer drugs, while in others the induction is of smaller magnitude, such as with diagnostic CT scans, environmental toxicity and chronic inflammation." (PMID 21325706, 2011). "However, the specificity of many cancer drugs for replicating cells creates a problem concerning appropriate tissues to sample for measuring γ-H2AX foci formation." (PMID 21325706, 2011). "The comet assay, micronucleus test, and γ-H2AX staining are not substitutes for other cytogenetic markers (i.e. the frequency of chromosome breaks) as markers of cancer susceptibility in this high-risk group." (PMID 17213827, 2007). "High γ-H2AX expression, as a marker of DNA degradation and the failure of its repair response, along with DNA double-strand break formation, was found in the biliary tracts of patients with BPMs and at even higher concentrations in patients with BPMs and cancer at the same time." (PMID 39064241, 2024). "Therefore, we tested whether overexpression of TS induced DNA damage in PanNETs by measuring expression of γ-H2AX in carcinoma developed in hTS/Men1–/– and Men1–/– mice." (PMID 36048542, 2022). "Given that 2-APCAs-treated cells exhibited significant cell cycle abnormalities (i.e., accumulation of cancer cells in the M-phase), the increased expression of γ-H2AX might be a consequence of the selective accumulation of cancer cells in the M-phase, as was evidenced earlier." (PMID 33503939, 2021). "Moreover, the sensitivity to OTX015 was also associated to DNA damage, as assessed by the strong and persistent upregulation of the histone H2AX phosphorylation at Serine 139, a known marker of genomic instability, this indicating the inability of cancer cells to repair DNA." (PMID 33806232, 2021). "Moreover, H2AX had been proved to be involved in cancer initiation and progression." (PMID 34497156, 2021). "To examine how FAK inhibition could alter the radiosensitivity, we measured the level of residual γ‐H2AX foci in cancer cells 24 h after radiation which correlates with the impairment of DNA repair and radiosensitivity of the irradiated PCCs in coculture with PSCs." (PMID 32705304, 2021). "In particular, we analyzed phosphorylated histone H2AX (γ-H2AX), which is a well-known marker of double-strand breaks, and replication protein A (RPA) and CHK1, which have previously been implicated in the DDR pathway induced by dl922-947 or AZD1775 in other cancer cell types." (PMID 33020398, 2020). "Histone H2AX, a variant of H2A protein play an important role as a guardian of the genome, and loss of H2AX may induce genomic instability with increased chance of cancer development." (PMID 27655674, 2017). "However, paradoxically, the phosphorylation of H2AX during cancer therapy could confer a survival benefit to cancer cells." (PMID 27643881, 2016). "Hence, we investigated the role of SUV39H2 and its relation to H2AX modification in human cancers." (PMID 25487737, 2014). "Treatment with doxorubicin or carboplatin induced DNA damage, as evidenced by γ-H2AX expression, and triggered apoptosis, as shown by cleaved PARP and Caspase3, in low DDB2-expressing cancer cells (e.g., MDA-MB-231, SK-BR-3, MDA-MB-468)." (PMID 41208896, 2025).
cancer (continued). "We examined γH2AX, which is the phosphorylation of Ser139 of histone H2AX and well-recognized as the biomarker of DSB, in BRCA1-proficient cancer cells." (PMID 40299557, 2025). "In senescent cells, it is unclear how SAHF-driven γ-H2AX inhibition, in response to external stimuli, affects SASP and apoptosis induction, and it would be interesting to investigate the impact of SAHF on cancer therapy." (PMID 38542327, 2024). "In fact, PBK can act on a variety of downstream molecules, such as p38, H3, H2AX, ERK1/2, MKP1, and Prx1, thus promoting the occurrence of cancer, development, metastasis, and drug resistance." (PMID 38460944, 2024). "Here, we present county-level, single-assay risk mapping results based on the H2AX histone modification genotoxicity assay (assay id: TOX21 H2AX HTRF CHO Agonist ratio), a potential in-vitro replacement for cancer relative potency factors." (PMID 39399012, 2024). "We have also shown, with the use of an alkaline/neutral version of the comet assay and γ-H2AX staining, that MM129, MM130, and MM131 sulfonamides exhibited genotoxic activity in four investigated cancer cell lines (HeLa, HCT-116, PC-3, and BxPC-3)." (PMID 36835469, 2023). "Furthermore, we tracked γ-H2AX foci in live cells upon intracellular delivery of the bivalent nanobody fused to the red fluorescent protein dTomato, making, consequently, this new cost-effective reagent useful for studying drug-induced replication stress in both fixed and living cancer cells." (PMID 34282773, 2021). "The phosphorylation of serine, located four residues from the C terminus of H2A histone family member X (H2AX), which is a marker of DNA double strand break, an alteration leading to genomic instability and, eventually, to cancer." (PMID 32268584, 2020). "After exposure of cancer cells to CPA, 4-OH-CPAUPO, as well as the PPA in concentrations up to 50 μM for HepG2 and 25 μM for MCF-7 for 24 h, the phosphorylation of H2AX (γH2AX), seen as fluorescent foci in cell nuclei, was measured." (PMID 32683510, 2020). "In contrast, only comparable, low levels of phosphorylated H2AX were visualized in both the vehicle- and FQI1-treated cells, consistent with low levels of DNA damage known to occur in cancer cells." (PMID 32539694, 2020). "The increased γ-H2AX level and olive tail moment suggest that TCTP knockdown sensitizes cancer cells to radiation-induced DNA damage." (PMID 30893896, 2019). "Our results suggest that the SUV39H2 inhibitors sensitize cancer cells to DOX by reduction of γ-H2AX levels in cancer cells, and collectively demonstrate that SUV39H2 inhibition warrants further investigation as a novel anti-cancer therapy." (PMID 30159125, 2018). "Histone H2AX is rapidly phosphorylated (γ-H2AX) in response to DSBs induced by ionizing radiation and a number of cancer chemotherapeutic agents." (PMID 30705876, 2018). "The serum purified histones were profiled for changes in histone PTMs and have shown a comparable pattern of modifications like acetylation (H4K16Ac), methylation (H4K20Me3, H3K27Me3, H3K9Me3) and phosphorylation (γ-H2AX and H3S10P) to paired cancer tissues." (PMID 28360947, 2017). "H2AX activation has also been noted a number of days after treatment with an HDAC inhibitor, suggesting that increased γH2AX expression precedes cancer cell death." (PMID 26683361, 2016).
cancer (continued). "Previously, the persistent accumulation of H2AX phosphorylation after cisplatin treatment and exposure to high-dose ionizing radiation was observed after REV3 depletion in cancer cells, suggesting the accumulation of irreparable DSBs." (PMID 25781640, 2015). "In the present study, we showed that the histone methyltransferase SUV39H2 methylates histone H2AX on lysine 134, and that this is critical for the production of γ-H2AX in cancer cells." (PMID 25487737, 2014). "In the present study, we demonstrate that SUV39H2 methylates histone H2AX, and that the H2AX methylation is critical for γ-H2AX accumulation in human cancer." (PMID 25487737, 2014). "In aged and cancer cells spontaneous metaphase-TIF are present in distinct chromatid (γ-H2AX on one telomere sister-chromatid) and chromosome (γ-H2AX on both telomere sister-chromatids) types, with chromatid-type being the more abundant form 7,53." (PMID 25171524, 2014). "Thus, H2AX could also be targeted to promote cancer cell death." (PMID 25003966, 2014). "In 12 cancer patients that experienced severe atypical NTT following radiotherapy, there was a failure to repair DNA double-strand breaks (DSB) as measured by γ-H2AX induction and persistence." (PMID 21491423, 2011). "We used flow cytometric analysis of γ-H2AX induction and removal to measure DNA DSB damage and repair in the PBL of cancer patients who had experienced excessive acute and/or late NTT after radiotherapy." (PMID 21491423, 2011). "Among the studied 17 genes, this is the first report of promoter methylation for CpG sites in H2AX, RNF8 and CYCS in human cancer." (PMID 21092294, 2010). "In AsPC-1 cancer cells, 32 was more effective than RSV at activating the DNA damage marker H2AX and promoting altered expression of cell-cycle regulatory proteins, which interfered with AsPC-1 cancer cells’ biological processes and effectively promoted apoptosis." (PMID 40005268, 2025). "Neurospheres, anchorage-dependent GBM cells and RPE-1 non-cancer cells were treated with CPZ, TMZ or their combination, then the presence of γ-H2AX foci, a readout of DSBs and thus DNA damage, was assessed using immunofluorescence and cytofluorimetric analysis." (PMID 39026284, 2024). "Nsp1 expression in cancer cells resulted in the down-regulation of several oncogenic or progrowth signaling pathways, including the mTOR and MAPK pathways, and up-regulation of the DNA damage marker p-H2AX, consistent with its anticancer activity." (PMID 39161732, 2024). "Since histone H2AX is transiently induced upon ATM activation, this results in a heightened damage response and increases in γH2AX foci formation, which in turn result in efficient induction of cancer-cell death." (PMID 36706121, 2023). "Consistent with the results of apoptosis analysis, DF5 activated the DNA damage marker H2AX more effectively than RSV in AsPC-1 and Capan-2 cancer cells, whereas no relevant effects on H2AX activation were observed with both compounds in BxPC-3." (PMID 36768301, 2023). "In contrast, some in vitro studies have suggested that the formation of γ-H2AX foci does not correlate with the sensitivity of cancer cells to α-radiation." (PMID 38140100, 2023).
cancer (continued). "Furthermore, we treated cells with cisplatin, ME, or both, and the expression of cancer pathway factors was assessed, including HSP90AB1, IGF1R, p-H2AX, MYC, and PTEN." (PMID 37180757, 2023). "Paclitaxel similarly resulted in an increased the level of γ-H2AX that could be attenuated by UCN-01 or MitoQ and rescued the impaired proliferation of paclitaxel-treated cancer cells." (PMID 34773075, 2022). "In our study, the expression of γ-H2AX was significantly more prominent in the background epithelium of carcinoma in PBM patients in comparison to non-carcinoma cases, indicating that DSBs exist more abundantly in the PBM mucosa surrounding cancer." (PMID 34372868, 2021). "Previous studies have reported that TOPK directly phosphorylates ERKs, histone H3 (Ser10), histone H2AX (Ser139), peroxiredoxin (Ser32), JNK (Thr183/Tyr185), and PRPK (Ser250), indicating that it is a promising target in cancer related to growth, DNA damage, the cell cycle, and apoptosis." (PMID 34066486, 2021). "While alpaca-derived nanobodies against γ-H2AX have already been generated, these tools did not allow for the specific unambiguous detection of γ-H2AX in irradiated cancer cells." (PMID 34282773, 2021). "Among the PBM cases, γ-H2AX expression was significantly higher in patients with carcinoma than in those without (median γ-H2AX-positive proportion: 21.4 % vs. 11.0 %, p = 0.031)." (PMID 34372868, 2021). "RNF168 expression and signaling is deregulated in tumors and cancer cell lines by mechanisms that include increased mRNA expression, downregulation of TRIP12 and UBR5 proteases, as well as reduced expression of enzymes that de-ubiquitinate ub-H2AX." (PMID 32182354, 2020). "We observed that AZD1775 and dl922-947, both alone and in combination, activated the DDR pathway, as indicated by the increase in expression of γ-H2AX, phospho-RPA32 Ser 4/Ser 8, and phospho-CHK1 Ser 345, and in line with what was previously found in other cancer cell types." (PMID 33020398, 2020). "Cell death induction of cancer cells treated with increasing combinations of replication and kinase (ATR and Chk1) inhibitory drugs was proportional to the appearance of pan-nuclear γ-H2AX pattern." (PMID 30871194, 2019). "And a slightly more γ-H2AX and H2Bub1 were still present in these USP22−/− H1299 cancer cells at 48 h post-irradition, indicating USP22 knockout impaired deubiquitination of H2Bub1 that may be required for prompt and correct DSB repair." (PMID 31842906, 2019). "There was a considerable difference in γ-H2AX accumulation between the cancer cells and the nontransformed HFF-1 cells, independently of the drugs or drug combinations used." (PMID 30871194, 2019). "Henceforward, owing to the intricate relationship between SUV39H2 and γ-H2AX formation, we speculated that SUV39H2 inhibition may be a promising potential drug target in various types of human cancer." (PMID 30159125, 2018). "In a treatment-naïve background, elevated γ-H2AX levels might mirror a strategy, namely the activation of the ATM-Chk2 pathway, cancer cells evolved to tolerate endogenous DNA damages arising upon oncogene-induced replication stress." (PMID 26544894, 2015). "A significant increase in the number of γ-H2AX foci was demonstrated in iHOXA10-treated cells, indicating that inhibition of HOXA10 impairs the HR DNA repair system, potentially keeping cancer cells from escaping death after anticancer treatment." (PMID 25061500, 2014). "While cancer cells, including HeLa, usually show low basal γ-H2AX expression without any stress, it was significantly increased in NTAPP-exposed HeLa cells." (PMID 24759730, 2014).
cancer (continued). "In fact, unlike senescent normal cells, H2AX expression is relatively high (2–20% of total H2A) in cancer cells as well as in growing NHFs (10%)." (PMID 21858116, 2011). "However, when phosphorylated histone H2AX (γ H2AX) was used as the marker, neither the conventional dose rate nor the ultra-high dose rate caused differences in damage to normal cells and cancer cell DNA." (PMID 39062469, 2024). "Importantly, the residual tumors of the combination group exhibited significantly higher levels of DNA damage (γ-H2AX) and apoptosis (Caspase-3) than the monotherapy groups, and apoptotic death occurred mainly in the cancer cells rather than in the stroma." (PMID 36765038, 2023). "Suppressed spontaneous and damage-induced mutagenesis, increased chromosomal aberrations, and H2AX phosphorylation also occur in cancer cells with REV7 depletion after treatment with various DNA-damaging reagents, indicating the involvement of REV7 in damage-induced mutagenesis in cancer cells." (PMID 36980607, 2023). "When the TMC>2, H2AX/micronuclei ratio and DSB recognition inhibition power are plotted against IARC carcinogenicity group classification, it appears that these parameters cannot predict carcinogenicity, and suggest that biomarkers reflecting cancer proneness are also needed." (PMID 35204751, 2022). "The endogenous (non-treated) U251 cells may contain γ-H2AX foci, which can be explained by spontaneous replication errors occurring in rapidly proliferating cells, e.g., in several cancer cell lines." (PMID 35370480, 2021). "The median positive proportions of γ-H2AX in cases with and without carcinoma were 21.4 % (range: 8.6–48.9 %) and 11.0 % (range: 0.8–70.7 %), respectively, and significantly higher in cases with carcinoma (p = 0.031)." (PMID 34372868, 2021). "This will significantly reduce the ubiquitination modification of histone H2A and H2A histone family member X (H2AX) after DNA damage, which will inhibit the response to DNA damage and reduce the stability of the genome, leading to the promotion of malignant cell transformation and cancer." (PMID 32175074, 2020). "On account of γ-H2AX production conferring poor prognosis in different types of cancer including TNBC and NSCLC, and our in vivo efficacy of SUV39H2 inhibition in two model systems, SUV39H2 may possess therapeutic potential in a wide range of human cancers." (PMID 30159125, 2018). "In our study, however, ZnPT treatment in cultured cancer cells did not induces DNA-damage responses, as reflected by the absence of γ–H2AX foci formation and failure to increase DNA-damage response-linked phosphorylation of ATM, H2AX, Chk1 and Chk2." (PMID 28086217, 2017). "Because pan-nuclear γ-H2AX pattern was hardly detectable in HFF-1 cells even after incubation with G+V for 72 h, and as the number of cells remained constant over time, we concluded that cancer cells might acquire a pan-nuclear γ-H2AX accumulation phenotype before cell death." (PMID 30871194, 2019). "As seen in HeLa cells, in both cancer cell types, which were almost completely lacking γ-H2AX staining before the treatment, we observed at the earliest time point (12 h) of HU treatment the appearance of γ-H2AX foci and progressively over time the nuclei of treated cells became pan-γ-H2AX stained." (PMID 30871194, 2019). "In our study, when cancer cells were exposed to drugs and ionizing radiation, low expression of XRRA1 could increase the phosphorylation of DNA repair pathway factors CHK1, CHK2, and ATM and reduce the expression of γ-H2AX, which is believed to participate in DNA repair in the nucleus." (PMID 29082250, 2017).